BCL2 (BCL2 apoptosis regulator)
Diseases named in the same sentence as BCL2 in open-access papers (continued):
Sharing a sentence is not in itself a finding about the gene and the disease.
cancer (continued). "Interestingly, the molecular network showing the highest percentage of deregulated genes has BCL2 as one of its central nodes and is associated with cancer, gene expression and neurological disease (Network 1)." (PMID 21143953, 2010). "Indeed, Aurora-A overexpression has been associated in cancer cells with spindle checkpoint dysfunction, increased resistance to paclitaxel and docetaxel, increased expression of Bcl-2 or of Bcl-xL." (PMID 21059223, 2010). "However, although Bcl-2 is an anti-apoptotic protein a rather paradoxical role of Bcl-2 have been described, showing an association between high Bcl-2 expression and improved survival in different cancers." (PMID 21304176, 2010). "The additional alterations of gene expression between cancer and normal cells include the anti-apoptotic oncogenes that encode Bcl-2 and Bcl-XL, and genes that encode the peripheral benzodiazepin receptor (PBR), the PBR-associated protein Prax-1, and mitochondrial creatine kinase." (PMID 20426862, 2010). "These preliminary results are consistent with recent reports of potential modulation of bcl-2 by xenoestrogens, supporting the concept that xenoestrogens may modulate cancer cell biology through associated changes in bcl-2." (PMID 20623010, 2010). "Bcl-2 and Bag-1 are associated with chemotherapy resistance in cancer cells." (PMID 18430249, 2008). "Additionally, Bcl-2 or NF-κB over-expression occurs in many cancer types and is associated with chemoresistance." (PMID 18522758, 2008). "Thus, it is suggested that prevention of depolymerization of cellular microtubules by taxanes causes phosphorylation of Bcl-2, thereby abrogating the normal anti-apoptotic function of Bcl-2 and initiating the apoptotic program in the cycling cancer cells." (PMID 11875716, 2002). "A strong Bcl-2 expression was found in the four cases of Brca2 -associated carcinomas." (PMID 11044356, 2000). "Additionally, the expressions of apoptotic and anti-apoptotic markers, including Bcl-2-associated X protein (Bax) and B-cell lymphoma 2 (Bcl-2), serve as prognostic indicators in cancer biology and may provide insights into the tumorigenic potential of ASCs." (PMID 40646808, 2025). "CK increases the ROS concentration in cancer cell mitochondria, causing the cancer cell mitochondria to lose membrane potential, increasing the expression of pro-apoptotic protein Bax and apoptotic protease Caspase-3/9 and reducing the expression of anti-apoptotic protein Bcl-2." (PMID 40422575, 2025).
cancer (continued). "Earlier and recent studies have showed that a high ratio of Bax to Bcl-2, activation of caspase family, including caspase-3, caspase-8 and caspase-9, as well as the loss of mitochondrial transmenbrane potiential are observed in monensin-induced apoptosis of several human cancer cell lines." (PMID 36896461, 2023). "Fe3O4 nanoparticles induce apoptosis in cancer cells by raising the quantity of reactive oxygen species (ROS) and intracellular calcium, as well as boosting the expression of caspase-3 and caspase-9 and decreasing the expression of Bcl-2, as well as causing direct DNA damage." (PMID 35867269, 2023). "Furthermore, for mice, the therapeutic performance of co-delivered siRNA/DOX@Ca2+ MSNs significantly increased tumor suppression more than DOX@MSNs and siRNA@Ca2+ MSNs, causing the transfected cancer cells to become sensitized to the apoptotic action of co-delivered DOX by Bcl-2 silencing." (PMID 34771642, 2021). "Therefore, LCL161 and ABT-263 are newly developed necroptosis inducers, and multiple clinical trials are underway to overcome drug resistance by antagonizing IAP proteins and BCL2 protein that is known to be linked to therapeutic failure and unfavorable prognosis in malignant tumors." (PMID 33239070, 2020). "Treatment with BIBR1532 of different cancer cell lines causes cell cycle arrest and apoptosis through activation of transcriptional pathways triggered by telomeres dysfunction, such as the increase of cell cycle inhibitor p21 and the unbalancing of Bax/Bcl-2 ratio." (PMID 33553285, 2020). "Crosstalk between TMPRSS13 and Bcl-2 associated pathways may contribute to the increased apoptotic effect we observed; the implications of such a connection are significant, as Bcl-2 is often upregulated in cancer, including CRC55." (PMID 32807808, 2020). "Similarly, Bcl-2, Kit, K-Ras, and Fos genes have been found to be associated with cancer." (PMID 33114225, 2020). "Studies had shown that apoptosis-related proteins were involved in regulating cancer cell metastasis, for example, pro-survival Bcl-2 over-expression was associated with enhanced cell invasion and migration while pro-apoptotic Bad and Bax could significantly suppress EMT45." (PMID 32873775, 2020). "Overexpressed BCL2 is associated with aberrant carcinoma growth in various human diseases, particularly with solid tumors, such as lymphomas, non-small-cell lung cancer, myeloma, and melanoma, having been recognized as targets for cancer therapy in the past three decades." (PMID 30682877, 2019). "On the basis of observations in epithelial cancers, N-cadherin may mediate drug resistance in leukaemic cells, at least in part, by activation of the pro-survival protein Bcl-2, or modulation of Sonic Hedgehog signalling, widely implicated in cancer stem cell function and maintenance." (PMID 30285678, 2018). "In addition, our data demonstrated that BCL2 inhibitors alone or in combination with EZH2 inhibitors may represent therapeutic strategies for ARID1A-mutated cancers." (PMID 30297712, 2018). "To confirm whether Bcl-2 promoter polymorphisms are related to cancer, we performed this meta-analysis, aiming to measure the correlation between Bcl-2 promoter polymorphisms and cancer susceptibility and prognosis." (PMID 28445963, 2017).
cancer (continued). "Similarly EV-associated miR-29c could induce apoptosis in recipient cancer cells by targeting and down regulating BCL-2 and MCL-1." (PMID 29657282, 2017). "How Bcl-2 is overexpressed in cancer cells is not fully understood; however, Bcl-2 overexpression is correlated with chromosomal deletions leading to loss of Bcl-2—targeting miRNAs such as miR-195, miR-24-2, and miR-365-2; gene amplification; and hypermethylation of the BCL2 gene." (PMID 26927133, 2016). "The mechanisms of tumorigenesis and carcinoma cell apoptosis induced by SD extracts may be associated with decreasing the ratio of bcl-2 and bax mRNA level, activating caspase-3, suppressing survivin, and decreasing the gene expression of COX-2, 5-LOX, FLAP, and 12-LOX mRNA." (PMID 25866543, 2015). "Cancer cells with high Bcl-2 expression may be less susceptible to apoptosis by cisplatin." (PMID 29147386, 2014). "Bcl-2 -938C>A polymorphism might become a novel maker in cancer susceptibility and prognosis." (PMID 25430556, 2014). "Thus, in cancer cells expressing low levels of Bcl2, cytotoxic therapy inducing DNA damage may cause death through apoptosis." (PMID 23653658, 2013). "A completely different explanation may rely on the different immunogenicity of mutated B-RAF and N-RAS or the respective induced effector molecules, as it has been recently suggested for the seemingly paradoxical association of a bcl-2 over-expression with an improved prognosis in cancer patients." (PMID 17311103, 2007). "bcl-2 might thus be one of the target genes involved in the oncogenesis related to Brca1 and its down-regulation may account for the increased apoptosis and the high proliferative rate observed in Brca1 -associated carcinomas." (PMID 11044356, 2000). "Our investigation focused on gene expression of TLR4, DC-SIGN, NF-κB, and BCL2 in healthy and cancer control groups." (PMID 42138288, 2026). "The balanced dual role of Bcl-2 in suppressing both autophagy and apoptosis makes it a central survival factor in cancer." (PMID 41596231, 2026). "The Bcl-2/Beclin1 complex regulates the balance between autophagy and apoptosis, playing a critical role in cancer cell survival and resistance to therapy." (PMID 41596231, 2026). "In cancer cells, Bcl-2 overexpression blocks mitochondrial translocation and activation of pro-apoptotic Bax, thereby directly inhibiting the intrinsic apoptotic cascade and promoting resistance to agents like STS." (PMID 41596481, 2026). "Both bioactive extracts induced apoptosis in cancer cells by downregulating the expression of the tumorigenesis genes bcl-2 and bcl-xL." (PMID 41595657, 2026). "STAT3 activation is achieved by increased phosphorylation at Tyr705, leading to enhanced expression of anti-apoptotic proteins like Bcl-2 and Mcl-1 and increased migratory, invasive, and metastatic potential of cancer cells." (PMID 41596231, 2026). "Upregulation of SLC25A6 expression induced by the glutaminase inhibitor CB-839 sensitized cancer cells to the Bcl-2 inhibitor ABT-199." (PMID 42020360, 2026).
cancer (continued). "It is worth noting that our previous results have shown the induction of apoptosis by the secretome of hAMSCs through the up-regulation of Bax and cleaved Caspase 3 and the down-regulation of Bcl2 in various cancer cells [9,10,]." (PMID 41488204, 2026). "An anti-apoptotic protein called Bcl2 is overexpressed in many cancer types, and by preventing chemotherapy-induced apoptosis, it aids in the development of treatment resistance." (PMID 41151762, 2025). "Fractions 2 and 3 caused a reduction in the levels of the anti-apoptotic protein Bcl-2 in both HepG2 and HT-29 cells and an increase in the pro-apoptotic enzyme caspase-3, which suppresses cancer cell proliferation." (PMID 41034324, 2025). "Bcl-2 is a pivotal molecule involved in the control of cell survival and cell death of various types of cancers." (PMID 39833890, 2025). "On the other hand, virtual interaction approach on BCPO indicated its binding affinity to anti-apoptotic proteins Bcl-2 and Mcl-1, which are often upregulated in various cancers." (PMID 40333803, 2025). "The SMAD complex then functions as a transcription factor in cancer cells, regulating the expression of genes like cyclin D1, BCL-2, and VEGF." (PMID 40485724, 2025). "This disruption of BCL-2-mediated apoptosis inhibition leads to the induction of programmed cell death in cancer cells." (PMID 40563591, 2025). "Further studies are required to elucidate the regulatory mechanisms underlying the mutual repression of ASCL1 and NEUROD1 along with the direct NEUROD1-mediated repression of BCL2 across different types of cancer and disease." (PMID 40082639, 2025). "The mitochondrial (intrinsic) apoptotic pathway in cancer cells is successfully started by this dual action of blocking survival signals (Bcl-2/Bcl-xL) and activating cell death executors (caspases, Bax)." (PMID 41465738, 2025). "Navitoclax (ABT-263), a BCL-2/BCL-XL family inhibitor originally developed as an anti-cancer drug, selectively eliminates senescent cells dependent on BCL-2 family survival signaling; however its use is limited by tissue toxicity." (PMID 41264145, 2025). "This means that many pro-apoptotic cancer therapies developed for malignancies (e.g., BCL-2 inhibitors) often possess inherent senolytic activity, making them immediately relevant for clearing pathogenic SnCs in aging tissues." (PMID 41614753, 2025). "This balance between pro- and antiapoptotic Bcl-2 proteins influences cancer cell survival and response to therapy." (PMID 40996961, 2025). "Our findings are consistent with previous literature showing that cucurbitacins trigger programmed cell death via apoptotic modulators such as caspase cascade, Bax, and Bcl-2 in different cancer cell lines in the 0–1000 nM concentration range." (PMID 40678417, 2025). "On the other hand, overexpression of the anti-apoptotic protein Bcl-2 frequently suppresses induction of MOMP in cancer cells, which has been suggested to contribute to resistance to chemotherapy." (PMID 41226559, 2025). "On the other hand, new interactions with RAF1 and MAPK1 seem to strengthen BCL2’s cancer-promoting activity." (PMID 40136517, 2025). "The mechanism of action of 1C was confirmed by molecular docking studies, where it showed a strong affinity for the BCL-2 protein, a key regulator of apoptosis in cancer cells." (PMID 40286078, 2025). "An unbalanced Bcl2/Bax ratio (Bcl2/Bax > 1) has been recognized in several studies as a signature of the acquisition of apoptosis resistance in cancer cells." (PMID 40818990, 2025).
cancer (continued). "1,25-Dihydroxyvitamin D3 3-glycoside, an active metabolite of vitamin D3, and stellasterol demonstrated strong binding affinities to B-cell lymphoma 2 (Bcl-2) anti-apoptotic protein and increased cell death in cancer cells." (PMID 40508113, 2025). "Strategies aimed at disrupting the binding of Bcl-XL and Bcl-2 to pro-apoptotic proteins offer promising solutions to overcome apoptosis evasion in Tx-resistant cancers." (PMID 41114937, 2025). "In recent years, PPI has been a focus in drug design, and PPI inhibitors have shown potential in preventing diseases such as Bcl2/Bax in cancer or Gp120/CCR5 in HIV." (PMID 40245093, 2025). "Oncolytic adenoviral vectors conjugated with peptide nucleic acids selectively target Bcl-2 gene G-quadruplexes, improving the safety and efficacy of cancer gene therapy." (PMID 40286158, 2025). "While the ubiquitous role of Bcl-2 in promoting cell survival is well-established, its precise mechanisms and clinical implications can vary significantly across different cancer types, necessitating a nuanced understanding for effective therapeutic targeting." (PMID 40841912, 2025). "The Bax/Bcl‐2 expression ratio for neuron‐glial culture (4.6 ± 0.3) was significantly higher than this ratio for B‐474 cancer cells and less than the Bax/Bcl‐2 expression ratio for fibroblasts." (PMID 39760157, 2025). "Experimental data showed that SNP/Qc treatment induced apoptosis in 3LL cancer cells, and subsequent analysis showed that Qc reduced the expression rate of Bcl-2/Bax." (PMID 40509418, 2025). "Polyphenols such as epigallocatechin-3-gallate have been found to inhibit cancer cell proliferation and regulate key apoptosis-related proteins (e.g., Bid, BAX, and Bcl-2), thereby promoting cancer cell death." (PMID 40871098, 2025). "CUR is recognized for its ability to induce Bax/Bcl2‐involved apoptosis in cancer cells, as evidenced by the elevated levels of Bax, Bax/Bcl2 and cleaved caspase‐3 in both CT26 and HCT116 cells treated with CUR at the 4‐h time point in our study." (PMID 39607347, 2025). "Gemini-curcumin also shifted the Bax/Bcl-2 ratio in favor of apoptosis, which underscores its ability to promote cancer cell death by modulating apoptotic pathways." (PMID 39861761, 2025). "The BCL2 gene family is also recognized for its contrasting roles in disease, with upregulation in CNS disorders and downregulation in cancers." (PMID 40310674, 2025). "Bcl-2 was considered in the study to be of broad importance to NHLs and the numerous studies where terpenoids induce apoptosis in various types of cancer by regulating Bcl-2." (PMID 40565145, 2025). "In this study, the protein–protein interactions (PPIs) of BCL2 with potential binding partners and their role in cancer was investigated." (PMID 40136517, 2025). "Our models showed that miRNAs and TFs are the greatest contributors to the explanation of BCL2 gene expression variation, conferring a predictive gain of 15–60% in 9 of our 21 cancers for miRNA and <25% in 11 of our 21 cancers for TFs." (PMID 40041206, 2025).